CDH1 (cadherin 1)
Diseases named in the same sentence as CDH1 in open-access papers (continued):
Sharing a sentence is not in itself a finding about the gene and the disease.
gastric adenocarcinoma (51 papers, 2005 to 2026). "From TCGA analysis, several frequently occurring alterations have been described in GS, gastric adenocarcinoma, including mutations in CDH1 and RHOA, as well as CLDN18:ARHGAP fusions." (PMID 38717153, 2024). "CDH1 mutation was more frequently identified in peritoneal carcinomatosis than in primary gastric adenocarcinoma." (PMID 36703611, 2023). "Expression of the MST3 and CDH1 genes was found to be correlated in gastric adenocarcinoma tissues, as a decrease in the expression of MST3 suppressed the expression of CDH1, which increased the migration of the cells." (PMID 40265380, 2025). "Cdh1-positive gastric epithelial cells derived from gastric adenocarcinoma, such as MKN-28 or NCI-N87 cells have previously been used to study HtrA-mediated Cdh1 cleavage, while investigations utilizing healthy human epithelial cells are not yet available." (PMID 39000189, 2024). "However, several CDH1 inactivation mechanisms (promoter methylation, microRNAs post-transcriptional regulation, glycosylation) can be associated with Lauren intestinal-type gastric adenocarcinoma and can also be present in early stages of neoplastic development, as shown by our results." (PMID 35925389, 2022). "We observed a significant reduction in CDH1 mutations in CCNE1-amplified gastric adenocarcinoma versus nonamplified gastric adenocarcinoma (2.9% vs. 16.4%, P = 0.0002) as well as a reduction in CLDN18:ARHGAP fusions (0% vs. 6.8%); however, the frequency of RHOA mutations were similar." (PMID 38717153, 2024).
gastric tumors (46 papers, 2011 to 2025). "CDH1 was significantly associated with Lauren staging, and gastric tumors with CDH1 mutations were more likely to be identified as diffuse tumors." (PMID 39870503, 2025). "Since there are no isoform-specific small molecule inhibitors of AKT3, we sought to identify an indirect route to target this protein in E-cadherin-deficient cells by identifying AKT3-associated genes in CDH1-low gastric tumours." (PMID 35406381, 2022). "According to the literature, about 7% of all the so‐far identified germline CDH1 mutations are present in non‐gastric tumors." (PMID 35277969, 2022). "In this study, we aimed to assess the overall frequency of CDH1 mutations in non-gastric tumors reported in literature so far." (PMID 34066044, 2021). "In conclusion, in comparison with our previous study, our results suggest that about 7% of the overall CDH1 mutations are present in non-gastric tumors." (PMID 34066044, 2021). "In this study, firstly, we reviewed the frequency of CDH1 germline mutations in non-gastric tumors, and we identified 54 alterations." (PMID 34066044, 2021). "Since the first report of CDH1 germline mutations in a Maori population from New Zealand with a strong cluster for gastric tumors, more information about this gene has been collected." (PMID 32886433, 2020). "Several cancers, including gastric tumors, show methylation of multiple genes including E-cadherin (CDH1), death-associated protein kinase (DAPK) and cyclin-dependent kinase inhibitor 2A (CDKN2A)." (PMID 23280118, 2013). "Several cancers, including gastric tumors, show methylations of multiple genes including E-cadherin gene (CDH1), death-associated protein kinase gene (DAPK) and CDKN2A." (PMID 22827846, 2012). "Patients with gastric neoplasms or CDH1 mutation undergoing RYTG between 2000 and 2021, with a minimum follow-up of 12 months, were interviewed to assess their functional and nutritional status and to measure their quality of life (QoL) with the GIQLI, EORTC-QLQ20 and EORTC-STO22 questionnaires." (PMID 41085883, 2025). "CDH1 missense mutations are more frequent in non-gastric tumors (48.2%), and other factors could play a synergistic role with missense mutations in the development of non-GCs." (PMID 34066044, 2021). "We identified 54 CDH1 germline mutations in non-gastric tumors." (PMID 34066044, 2021). "Furthermore, proteomic analysis has shown that the AKT and EGFR pathways are upregulated in CDH1-mutated gastric tumours." (PMID 31540244, 2019). "This multicenter study evaluated the association of 9 single nucleotide polymorphisms (SNP) in AXIN2 and CDH1, representing genes consistently altered in breast and gastric tumors, with NSCL ± P in 223 trios (father, mother and patient with NSCL ± P) by transmission disequilibrium test (TDT)." (PMID 28376813, 2017). "There were also miR-506 and CDH1 up-regulations while SNAI2 down-regulation in gastric tumor cells resulted in reduced cell migration." (PMID 37051101, 2023). "We also performed IHC in gastric tumors of ten index cases from this series known to be wild-type for the CDH1 and CTNNA1 genes and for whom tumor specimens were available, and catenin alpha-1 expression was retained in both normal and tumor cells." (PMID 37686589, 2023). "In order to assess the protein expression level of E-cadherin (CDH1 gene product) in the index case gastric tumor tissue, we have performed an immunohistochemistry by using a monoclonal antibody directed against the Nt domain of E-cadherin." (PMID 36011265, 2022).
gastric tumors (continued). "Pathway metagene expression of 415 TCGA gastric tumours was statistically correlated with CDH1 expression." (PMID 30066183, 2019). "CDH1 is a marker of an epithelial phenotype and is often lost in gastric tumours due to the process of epithelial to mesenchymal transformation (EMT) and is a negative prognostic marker." (PMID 21781349, 2011). "In 42% of gastric tumours analysed, CDH1 to CDH3 switch was observed." (PMID 37372088, 2023). "Gene expression analysis of gastric tumour samples from The Cancer Genome Atlas (TCGA) stomach adenocarcinoma (STAD) cohort revealed that the expression of the AKT3 isoform (but not AKT1 or AKT2) is inversely correlated to the expression of CDH1 in gastric tumours." (PMID 35406381, 2022). "We first examined the correlation between individual HDACs and CDH1 expression in gastric tumors." (PMID 35008338, 2021). "In addition, the UBE2T knockdown-induced increase in CDH1 (E-Cadherin) also inhibits gastric tumor formation and growth." (PMID 28427240, 2017). "Normal gastric mucosa and gastric tumor tissues were compared for ARID1A, CDH1, c-MET and PIK3CA mRNA expression using RT-qPCR." (PMID 26334097, 2015). "CDH1 and CDH3 mRNA expression was obtained from 42 gastric tumours’ RNA-seq data." (PMID 37372088, 2023). "In these gastric tumour samples, there was a non-significant correlation between AKT1 and CDH1 expression (correlation 0.081, p = 0.1)." (PMID 31540244, 2019).
pancreatic ductal adenocarcinoma (46 papers, 2010 to 2026). An infiltrating adenocarcinoma that arises from the epithelial cells of the pancreas. "For example, in RAS‐driven pancreatic ductal adenocarcinoma, BACH1 directly represses the expression of the transcription factor FOXA1, which is known to activate the expression of CDH1 encoding E‐cadherin, CLDN3, and CLDN4 to induce the EMT and tumor metastasis." (PMID 33932125, 2021). "Furthermore, CDH1, the adhesion molecule involved in cell-to-cell cohesion, cell-to-cell recognition, and epithelial polarity, is known to be regulated by TGFβ in pancreatic ductal adenocarcinoma." (PMID 29285254, 2017).
asthma (44 papers, 2013 to 2026). "For example, it is well established that CDH1 gene polymorphisms are associated with airway remodeling, inflammation and lung function decline in individuals with asthma." (PMID 35590254, 2022). "They found that EST exposure to more than 5 cigarettes/day and the presence of CDH1 AA/CA genotypes had a significantly increased risk for childhood asthma (OR 1.53; 95% CI 1.08–2.17), suggesting a role of gene and environment interactions in asthma risk." (PMID 25276428, 2014). "E-cadherin (CDH1) gene polymorphisms are associated with airway remodelling, inflammation and lung function decline in individuals with asthma." (PMID 23521807, 2013). "CDH1 SNPs are associated with epithelial E-cadherin expression and suggest that epithelial adhesion is an important contributor to airway remodeling and lung function in asthma." (PMID 23521807, 2013). "We also note the substantial induction of CDH1, an epithelial derived adhesion factor that plays an important role in airway remodeling and lung function in asthma." (PMID 35590254, 2022). "Moreover, polymorphisms in the CDH1 gene (included in the family of E-cadherins) have been described, being associated with airway remodeling, inflammation, and forced expiratory volume in 1 s (FEV1) decline in asthma patients." (PMID 32899814, 2020).
esophageal squamous cell carcinoma (44 papers, 2009 to 2025). Esophageal squamous cell carcinoma (ESCC) is a type of esophageal carcinoma (EC) that can affect any part of the esophagus, but is usually located in the upper or middle third. "MiR-92a targeted suppressed E-Cadherin (CDH1) expression to promote LNM in esophageal squamous cell carcinoma." (PMID 26657296, 2016). "Furthermore, miR-25, an up-regulated miRNA in our sample of SCI individuals, may promote migration and invasion of esophageal squamous cell carcinoma cells by suppressing the expression of the CDH1 gene." (PMID 31444279, 2019).
ovarian tumor (43 papers, 2003 to 2025). "In an ovarian tumor cell line, it was reported that PTTG1 induces EMT by downregulation of E-Cadherin (CDH1 gene), the master regulator of this process." (PMID 36230799, 2022).
head and neck squamous cell carcinoma (41 papers, 2014 to 2026). A squamous cell carcinoma that arises from any of the following anatomic sites: lip and oral cavity, nasal cavity, paranasal sinuses, pharynx, larynx, and salivary glands. "For example, it was shown that BMI1, a component of PRC1, acted cooperatively with TWIST1, one of EMT-related transcription factors (EMT-TFs), to repress CDH1 during EMT in head and neck squamous cell carcinoma." (PMID 33779563, 2021). "CDH1 modulates the status of head and neck squamous cell carcinoma, according to these studies." (PMID 36090900, 2022). "In head and neck squamous cell carcinoma (HNSC) patients, CDH1 mRNA expression was found to be negatively correlated with MSI (HNSC-814.6.2.N.3.0.0.2.2.3)." (PMID 41048343, 2025).
meningioma (41 papers, 2005 to 2025). A generally slow growing tumor attached to the dura mater. "And Neurofibromin (NF2) deficiency and low E-cadherin (CDH1) levels have been shown to increase ferroptosis vulnerability in meningiomas." (PMID 37091802, 2023). "The few studies that have directly assessed VS and meningioma indicate similarities in NF2 gene pathogenic variants and in gene expression related to angiogenesis and tumour suppression (PDGFD, CDH1 and SLIT2)." (PMID 41437121, 2025). "Variants typical for angiomatous (brain) meningioma are PIK3CA, KIT, PTPN11, CDH1, SMAD4, and SMARCB1; the variants typical for psammomatous meningioma are APC, FGFR2, HNF1A, STK11, and JAK3." (PMID 38476782, 2024). "We interrogated our transcriptomic data set for the expression of two genes associated with meningiomas and EMT: VIM encoding for vimentin (mesenchymal) and CDH1 encoding for E-cadherin (epithelial)." (PMID 38102708, 2023). "This study showed a slightly lower frequency of LOH in meningioma (in 15.3%), but also a tendency of a slight LOH frequency increase with higher grades, suggesting that the LOH of CDH1 gene plays a role in meningioma progression." (PMID 33915799, 2021). "The observed over-expression of E-cadherin (CDH1) in the current study represents an additional factor in favor of preventing malignant progression in meningiomas grades I and II." (PMID 26950155, 2016). "Our group previously showed similar results, who found the LOH of CDH1 gene in 37.5% of meningioma." (PMID 33915799, 2021). "Gross deletions of the CDH1 gene were also detected in 32% of investigated meningiomas." (PMID 27429002, 2016). "The down-regulation miR-21, combined with the overexpression of miR-34a, miR218, PTEN and E-cadherin (CDH1) could explain the benign nature of meningiomas (grades I and II) and represent barriers for grades I and II tumors from malignant progression." (PMID 26950155, 2016). "Furthermore, E-cadherin downregulation has been described as one of the main molecular events responsible for meningioma development, and alterations within the CDH1 gene have been found in this neoplastic disease, namely loss of heterozygosity (LOH) and genomic instability." (PMID 34680444, 2021). "This research has showed that genes that are involved in cadherin switch, CDH1 and CDH2, play a role in meningioma progression." (PMID 33915799, 2021). "The study of the CDH1 gene in various brain tumors showed that 14.3% of primary brain tumors had LOH and that this genetic change was mainly related to meningioma (31% of meningioma samples showed LOH)." (PMID 33915799, 2021). "Microsatellite markers specific for two different Wnt genes that were used (CDH1, AXIN1), revealed a fraction of meningiomas with MSI." (PMID 27429002, 2016). "DEG analysis identified 250 and 68 significantly overexpressed genes in the VS and meningioma tumour samples respectively compared to their control tissues, including six significantly co-overexpressed genes: COL1A, ERBB2, SLFN12, SLIT2, PDGFD and CDH1." (PMID 41437121, 2025). "Genetic changes of CDH1 and CDH2 are present in all meningioma grades." (PMID 33915799, 2021). "We showed that genes involved in cadherin switch, CDH1 and CDH2, may play a role in the development and progression of meningiomas, where both genes are involved and the basis for defective EMT has been established." (PMID 33915799, 2021). "Therefore, we can speculate that CDH1 and CDH2 genes may represent a useful prognostic marker of meningioma progression, especially since genetic changes occur in benign stages and increase their frequency by transitioning to malignant forms (especially LOH in the CDH2 gene)." (PMID 33915799, 2021). "E-cadherin (CDH1) was included to assess and compare the expression in non-malignant meningiomas grades I and II with normal dura (N and NN)." (PMID 26950155, 2016).
head and neck cancer (40 papers, 2010 to 2025). A primary or metastatic malignant neoplasm affecting the head and neck. "CDH1 promoter hypermethylation in head and neck cancer cells can suppress E‐cadherin expression and increase ferroptosis susceptibility." (PMID 40866937, 2025). "Head and neck cancer cells with DNA hypermethylation at CDH1 gene promoter reduce the production of e-cadherin (CDH1-encoded) and are more sensitive to iron." (PMID 37576601, 2023). "DNA hypermethylation of CDH1 gene promoter in head and neck cancer cells repressed E-cadherin (encoding by CDH1) expression and increased ferroptosis susceptibility." (PMID 35174081, 2022). "A tumoral defect of regulation of CDH1(Δ11) with a considerable increase in its level of expression has been involved in the tumorigenesis of head and neck cancers." (PMID 41154377, 2025). "The methylation array of 4,608 genes (duplicate on chip) that we used in this study included the majority of genes which have previously been associated with head and neck cancer (e.g., DAPK, MGMT, and CDH1, etc.)." (PMID 25197641, 2014). "Furthermore, it has been shown in head and neck cancer that patients with CDH1 hypermethylation have significantly better overall survival than those without hypermethylation." (PMID 21203466, 2010). "DNMT1 inhibitor 5-azaCdR decreases cadherin-1 (CDH1) methylation levels, increases e-cadherin expression, and decreases ferroptosis sensitivity in head and neck cancers." (PMID 40327848, 2025). "The hypermethylation of CDH1 gene was considered to be a bad prognostic factor in tongue cancer and ATM gene hypermethylation was connected with poorer prognosis in head and neck cancers." (PMID 24782031, 2014). "The epigenetic alterations of CDKN2A (p16; located at 9p21), CDH1 (16q22.1), FHIT (3p14.2), RAR-β (3p24.2), and ATM (11q22.3) have been found to be related to clinical prognosis in cancer of the head and neck." (PMID 24782031, 2014). "Similarly, in head and neck cancer, ZEB1 overexpression or cadherin 1 (CDH1) silencing increases ferroptosis sensitivity." (PMID 40075648, 2025). "In head and neck cancer, aberrant promoter methylation has been found in a wide variety of genes including p14ARF, p15, p15INK4B, p16, p16INK4A, ATM, DCC, DAPK, MINT1, MINT2, MINT27, MINT31, RARbeta, CDH1, cyclin A1, cytoglobin, RASSF1A, LHX6, MLH1, MGMT, and CDKN2A." (PMID 22645613, 2012).